CDH17 (cadherin 17)
Diseases named in the same sentence as CDH17 in open-access papers (continued):
Sharing a sentence is not in itself a finding about the gene and the disease.
tumor (continued). "The pooled evidence therefore shows CDH17 as a pro-tumorigenic factor that drives phenotypic changes favouring tumour initiation and progression." (PMID 41155133, 2025). "Our study also found that treatment with CV1 in combination with CDH17-CAR-NK92 led to an increase in CD69+ and CD86+ macrophages, potently implicating the enhanced antitumor activity of tumor-associated macrophages." (PMID 40487639, 2025). "Our results demonstrate that CV1 can significantly improve the anti-tumor effects of CDH17-targeting CAR-NK cells." (PMID 40487639, 2025). "To date, no systematic review (SR) has thoroughly synthesised the evidence regarding the mechanistic and functional relationship between CDH17 and Wnt/β-catenin signalling across various tumour contexts." (PMID 41155133, 2025). "Therefore, at first glance, CDH17 may be associated with less aggressive tumor behavior." (PMID 40725206, 2025). "We engineered OMVs with cadherin 17 (CDH17) tumour‐targeting nanobodies, enhancing tumour selectivity and efficacy while reducing adverse effects." (PMID 40240911, 2025). "Surprisingly, high CDH17 immunohistochemical expression in tumor emboli was correlated with T3 stage." (PMID 40725206, 2025). "Conversely, in the subcutaneous tumors of mice bearing ASPC1 cells, CDH17 expression is notably distributed around the tumor cells." (PMID 40487639, 2025). "We genetically modified OMVs with CDH17‐targeting nanobodies, imparting them with tumour‐homing capabilities and improved antitumour performance and biosafety." (PMID 40240911, 2025). "A comparison of tumor growth showed that CDH17 x GUCY2C BsADC treatment resulted in significant tumor regression compared to CDH17-ADC or GUCY2C-ADC treatment." (PMID 40721409, 2025). "The number of cells expressing CopGFP was increased in tumor tissues treated with CDH17-CAR-NK92 cells compared to the C9-CAR-NK92 cell groups." (PMID 40487639, 2025). "While evidence indicates that CDH17 functions as an upstream regulator of Wnt/β-catenin signalling, findings are inconsistent across tumour types, limiting the assessment of CDH17 as a biomarker or therapeutic target for Wnt pathway in cancer." (PMID 41155133, 2025). "We further evaluated the in vivo anti-tumor activity of CDH17 x GUCY2C BsADC in a mouse xenograft tumor model." (PMID 40721409, 2025). "An in vivo study also demonstrated CDH17 silencing redistributed β-catenin to the cytoplasm, reduced cyclin D1 levels, and increased Rb in tumour tissues." (PMID 41155133, 2025). "This fact highlights CDH17’s role in the intrinsic cellular mechanism of tumor progression; the phenotypic characteristics responsible for a low-grade behavior depend on the functionality of intercellular junctions." (PMID 40725206, 2025). "The first key aspect involves the specific engineering of CAR-T cells recognizing CDH17 or SSTRs, enhancing treatment efficacy through precise tumor cell targeting with minimal damage to healthy tissues." (PMID 41200177, 2025). "There was an increased presence of CopGFP-expressing cells in tumor tissues treated with CDH17-CAR-NK92 cells compared to the C9-CAR-NK92 cells group." (PMID 40487639, 2025). "CDH17-targeted CAR-NK cells combined with CV1 demonstrate enhanced anti-tumor activity in GI cancers by promoting macrophage activation and increasing M1 macrophage numbers, offering a promising therapeutic strategy." (PMID 40487639, 2025). "Multivariable Cox regression confirmed CDH17 expression in tumor emboli as an independent prognostic factor, indicating an approximately twofold risk of death." (PMID 40725206, 2025). "Further examination of CDH17 in both cells and tumor tissues revealed a marked increase in the percentage of CTC-TJH-01 cells cultured in suspension." (PMID 39994505, 2025). "This selective targeting is further supported by the fact that CAR-NK cells do not accumulate in CDH17-expressing organs where the pattern of CDH17 expression is different from tumor cells." (PMID 40487639, 2025).
tumor (continued). "Next, we wanted to clearly demonstrate the improved tumour selectivity of Nb289‐OMVs in CDH17+ tumour models; to this end, we encapsulated IR700 into the engineered OMVs." (PMID 40240911, 2025). "Mechanistically, CDH17 appears to facilitate tumour-stromal interactions in GC through homophilic adhesion and interaction with DSC1, thereby promoting migration and invasion." (PMID 41155133, 2025). "This indicates that CDH17 sustains cancer stem cell–like properties, thereby supporting self-renewal and tumour initiation, and finally reduces colony formation." (PMID 41155133, 2025). "In vivo, CDH17 suppression resulted in 80–95% tumour growth suppression (Mean Difference (MD) = −96.67, 95% CI: [−144.35, −48.98], p < 0.0001), with immunohistochemistry confirming cytoplasmic β-catenin sequestration and lower cyclin D1 levels." (PMID 41155133, 2025). "As expected, CV1 significantly improved the anti-tumor effects of CDH17-CAR-NK92 cells against the ASPC1 tumor model." (PMID 40487639, 2025). "The results demonstrated that CDH17-targeting CDH17-CAR-NK92 cells significantly impeded tumor growth and extended mouse survival compared to the C9-CAR-NK92 cells." (PMID 40487639, 2025). "CDH17 expression was evaluated in the tumor core, invasive front, tumor emboli, and lymph node metastases." (PMID 40725206, 2025). "The Kaplan–Meier univariate analysis showed a statistically significant correlation between CDH17 immunohistochemical expression and OS in tumor emboli (p = 0.034), high CDH17 levels signifying a poor prognosis." (PMID 40725206, 2025). "Statistical analysis showed several correlations between CDH17 immunohistochemical expression (in tumor core/tumor invasive front/tumor emboli/lymph node metastases) and clinicopathological features." (PMID 40725206, 2025). "Through the Kaplan–Meier univariate analysis, we found a statistically significant correlation between CDH17 immunohistochemical expression in tumor emboli and OS, with high CHD17 being correlated with a poor prognosis." (PMID 40725206, 2025). "Analysis of M Score demonstrated a significantly higher expression level of CDH17 in tumor tissues compared to adjacent normal tissues (p = 0.0011." (PMID 39617741, 2024). "Inhibiting CDH17 has been shown to suppress tumor growth and metastasis, suggesting that CDH17 can be used as a biomarker to predict cancer prognosis and as a target for cancer intervention." (PMID 39617741, 2024). "The study findings demonstrate that ICG/EVs enable rapid tumor imaging in a CDH17-positive GC model and induce significant antitumor PTT effects upon irradiation." (PMID 38675228, 2024). "To establish a bacteria delivery strategy targeting tumor tissues with CDH17 nanobody, we engineered the nanobody Nb289 onto the surface of non‐pathogenic E. coli MG1655." (PMID 38888519, 2024). "Collectively, these findings suggest that mild‐temperature PTT mediated by biohybrid bacteria targeting CDH17 can partially ablate murine tumor growth." (PMID 38888519, 2024). "We have demonstrated that nanobody‐engineered MG1655 exhibits great tumor‐homing ability towards CDH17‐expressing cancer models, and the biohybrid bacteria (Nb289‐MG1655‐CR) exhibit an excellent killing effect on CDH17‐positive cancer cells." (PMID 38888519, 2024). "Our results demonstrate that the NIR-II imaging probe E8-IR800CW effectively images subcutaneous tumors of CRC expressing CDH17 in nude mice and allows for imaging-guided precise tumor removal." (PMID 38911825, 2024). "Taken together, these results for NIR-II imaging and fluorescence-guided precise tumor excision suggest that E8-IR800CW can specifically image CRC tumors expressing CDH17 and can potentially be used to guide surgical resection." (PMID 38911825, 2024). "IHC was conducted to assess CDH17 expression on tumor tissues obtained from 150 retrospective CRC cases." (PMID 39617741, 2024).
tumor (continued). "Given our findings, with a higher frequency of CDX2 than CK20 and especially prevalent GPA33 and CDH17 expression, further studies of this tumor subtype would be of value." (PMID 37349623, 2024). "Immunostaining in CRC cell lines (HT115 and HCT116) and CRC xenograft tissues induced with the same cell lines further confirmed the membrane expression of CDH17 on tumor cells." (PMID 38911825, 2024). "Collectively, this platform consisting of CDH17 nanobody-engineered EVs and CR dyes provides a novel tumor theronostic system, and holds great promise for clinical translation." (PMID 37993888, 2023). "Cadherin 17 (CDH17) is a calcium-dependent cell adhesion glycoprotein involved in tumor invasion and metastasis." (PMID 37993888, 2023). "In HBV-related HCC, cadherin 17 (CDH17) is significantly correlated with CK19 in primary tumor tissue." (PMID 35725470, 2022). "In the present study, we labeled CDH17 nanobody E8 with IR-800 through site specific conjugation and tested the conjugate for imaging of CDH17-positive tumor model." (PMID 36435809, 2022). "Taken together, these data indicate that CDH17 ‘high-methylation’ stage II CC defines an immunologically ‘cold’ tumour subset within stage II CC." (PMID 36612154, 2022). "Hypermethylated CDH17 conferred high risk of disease recurrence and was associated with over-activity of oncogene signalling pathways, such as KRAS and low anti-tumour immune activity." (PMID 36612154, 2022). "The authors demonstrated, by in vitro and in vivo experiments (using autochthonous mouse models), that VHH1-CAR-T cells (CDH17 CAR-Ts) were cytotoxic to both human and mouse tumor cells in a CDH17-dependent manner." (PMID 36010987, 2022). "In the present study, the prominent anti-tumor effect of E8-PE38 immunotoxin on a CDH17-positive PDX model strongly supports the clinical translation for this novel therapeutic modality in GC therapy." (PMID 36435809, 2022). "By iAtlas analysis, an increased number of ‘IFNdominant’ immune subtype cases were seen in the CDH17 ‘high’ versus ‘low’ methylation tumour subgroups." (PMID 36612154, 2022). "The same team has demonstrated a dual amperometric bio-assay for the concurrent determination of CDH-17 and IL-13Rα2, tumor markers responsible for colorectal and breast cancers, respectively." (PMID 32079119, 2020). "A review of the literature revealed that CDH17, CNTN-1 and IGF2BP1 were associated with tumor progression and drug resistance and were identified as potential candidates for further analysis." (PMID 31427725, 2019). "From the top parenchymal networks, we selected two targets, CD147 and CDH17, that were found in malignant tumor invasion and tumor metastasis networks, respectively." (PMID 29899869, 2018). "To cross-validate the results of the IPA®, we set out to confirm the identification and topology of CD147, CD44, and CDH17 depicted in tumor invasion and tumor metastasis networks." (PMID 29899869, 2018). "Subsequent IHC analysis validated the localization of the human CDH17 in the tumor xenograft parenchyma." (PMID 29899869, 2018). "In conclusion, the present study identifies that CDH17 is an actual oncogene and plays a major role in cell proliferation and tumor growth in GC through integrin-Ras/Raf/MEK/ERK signaling." (PMID 24465527, 2014). "One week after tumor inoculation, when the tumor had reached approximately 100 mm3, we performed an intratumoral injection of CDH17 shRNA or mock vector at a dose of 109 viral particle/injection at the tumor site." (PMID 23554857, 2013). "In mice, shRNA-mediated CDH17 knockdown markedly inhibits tumor growth; intratumoral injection of CDH17 shRNAs results in significant antitumor effects on transplanted tumor models." (PMID 23554857, 2013). "In tumor-bearing mice, local delivery of lentiviral based CDH17 shRNA inhibited tumor growth, showing a striking suppression effect on tumor formation." (PMID 23554857, 2013).
tumor (continued). "Most strikingly, combined Lic+cis treatment completely abrogated lung metastasis of MHCC97L (0 out of 6 animals), exemplifying the anti-metastatic potential of Lic5 antibody by inhibiting the CDH17 functions in primary HCC tumor." (PMID 24039755, 2013). "We have also treated tumor-bearing nude mice with lentivirus harboring short hairpin RNA (shRNA) against CDH17 and this treatment resulted in regression of developing tumor xenografts." (PMID 24039755, 2013). "To search for new cures for aggressive HCC, we have observed an overexpression of CDH17 in HCC tumors and this abnormal expression is associated clinically to advanced tumor stage and presence of venous infiltration in these patients." (PMID 24039755, 2013). "Our previous studies have demonstrated CDH17 as an oncofetal molecule with confirmed tumor-inducing potentials and tumorigenic properties in HCC that Wnt/β-catenin pathway is its downstream pathway leading to tumorigenesis." (PMID 24039755, 2013). "As a prognostic factor, CDH17 expression showed a tendency towards an indicator for unfavorable survival in multiple patient cohorts, even after controlling for tumor stage." (PMID 23554857, 2013). "Examination of the tumor cells by CDH17 IHC demonstrated remarkable down-regulation of intended CDH17 target in the shCDH17 treated cells (P<0.05)." (PMID 23554857, 2013). "Western blots analysis confirmed high CDH17 protein expression in AGS (established from a primary tumor) and MKN-45 (metastatic)." (PMID 23554857, 2013). "Univariate analyses showed an association between overall survival and tumor site, histological differentiation, TNM stage and CDH17 expression." (PMID 23554857, 2013). "CDH17 promotes tumor growth through the Ras/Raf/MEK/ERK and β-catenin/GSK-3β signaling pathways." (PMID 41595482, 2026). "Additionally, our results agree with those reported in the literature, considering CDH17 immunohistochemical expression throughout the entire tumor mass." (PMID 40725206, 2025). "We aim to evaluate both experimental and clinical evidence on whether modulating CDH17 affects tumour behaviour through Wnt-related mechanisms." (PMID 41155133, 2025). "Taken together, these findings suggest that CV1 may enhance the anti-tumor effect of CDH17-CAR-NK92 cells by increasing the number of M1-phenotype macrophages and enhancing overall macrophage activation in the tumors." (PMID 40487639, 2025). "Moreover, we observed that CDH17 x GUCY2C BsADC treatment resulted in increased MDA and 4-HNE levels in tumor tissue compared to CDH17-ADC or GUCY2C-ADC treatment." (PMID 40721409, 2025). "It is also possible that CDH17 contributes more strongly to functional tumour behaviour (e.g., Wnt activation, progression, EMT, stemness) than to baseline stage or sex-stratified progression, underscoring the need for larger clinical studies to clarify these associations." (PMID 41155133, 2025). "Moreover, the endocytic activity of the CDH17 monoclonal antibody is weak; although it is highly expressed in tumors, ineffective internalization leads to weak anti-tumor activity." (PMID 40721409, 2025). "Notably, CDH17-CAR-NK92 cells significantly inhibited tumor growth in mice compared to C9-CAR-NK92 cells." (PMID 40487639, 2025). "Given that CDH17-targeting CDH17-CAR-NK92 therapy showed excellent anti-tumor activity in the CDX model, we next investigated whether CDH17-CAR-NK92 therapy could obtain similar results in a PDX model." (PMID 40487639, 2025). "In this study, we systematically review and meta-analyse the relationship between CDH17 and Wnt/β-catenin signalling in human cancers and evaluate whether CDH17 modulation affects tumour behaviour through Wnt-related mechanisms." (PMID 41155133, 2025). "However, high CDH17 levels in tumor emboli correlated with advanced T stage and poorer overall survival." (PMID 40725206, 2025).
tumor (continued). "Therefore, in this study, we aimed to combine a checkpoint inhibitor against the CD47–SIRPα axis that has not been previously utilized in combination with CAR-NK therapy to enhance the anti-tumor efficacy of CDH17-targeted CAR-NK cells." (PMID 40487639, 2025). "We reiterate that our study analyzed CDH17 expression in four different locations: the tumor core, the tumor invasive front, the tumor emboli, and the lymph node metastasis, thus providing comprehensive insight into the dynamics of this intercellular adhesion molecule." (PMID 40725206, 2025). "Furthermore, in vivo data reinforces these findings: two studies reported significant reduction in tumour volumes following CDH17 KD." (PMID 41155133, 2025). "The results indicated that the high levels of CDH17 immunohistochemical expression in tumor emboli (p = 0.028), with a hazard rate (HR) of 2.003 (95% CI: 1.077–3.723), may function as an independent prognostic factor." (PMID 40725206, 2025). "Collectively, these findings show CDH17 as a critical upstream effector sustaining Wnt/β-catenin signalling, cancer progression, tumour proliferation, stem cell properties, and metastasis, and support CDH17 inhibition as a promising therapeutic target across multiple cancer types." (PMID 41155133, 2025). "A significant upregulation of CDH17 is observed in tumor tissues across PDAC, GC, and CRC." (PMID 40487639, 2025). "We also disclose that CV1 could significantly enhance the anti-tumor effect of CDH17-CAR-NK92 cells, with one plausible mechanism being the enhancement of macrophage activation." (PMID 40487639, 2025). "Here, we evaluated the tumor morphology and immunohistochemical expression of CDH17 and CLDN18 in 25 CD-SBNs and potential relationships with gastric differentiation as indicated by MUC5AC and MUC6 immunohistochemistry, wnt pathway mutations, and mismatch repair gene protein immunohistochemistry." (PMID 39164422, 2025). "Furthermore, our findings highlight the potential of combining CDH17-targeting CAR-NK92 cells with CD47 blocker CV1 to augment the anti-tumor effects." (PMID 40487639, 2025). "CDH17 expression, particularly in the tumor emboli, could serve as a valuable prognostic biomarker in CRC with LVI." (PMID 40725206, 2025). "This work developed a biohybrid bacterial system through genetic engineering and biomaterial hybridization in which CDH17 nanobodies are engineered onto the bacteria for tumor targeting and a photothermal material croconium (CR) dye is conjugated on bacteria for PTT induction." (PMID 38888519, 2024). "Overall, these findings suggest that the nanobodies Nb289 and Nb535, identified through deep sequencing, hold potential for use in tumor models expressing both human and murine CDH17 antigens, thereby extending the applications of CDH17 nanobodies to a certain extent." (PMID 38888519, 2024). "Given the strong in vitro binding activity of Nb289‐engineered MG1655 to CDH17, we further examined whether the engineered bacteria could effectively target tumor mass in a tumor‐bearing mouse model after systemic administration." (PMID 38888519, 2024). "Our findings unraveled that E8 nanobody could efficiently target tumor CDH17 molecule and produce specific fluorescence imaging signals within a short time in the tumor." (PMID 36435809, 2022). "However, this was accompanied by significantly higher TGFB1 levels and unchanged IL17 levels, despite evidence of increased Th17 cell recruitment in CDH17 high versus low-methylation tumours." (PMID 36612154, 2022). "Finally, CDH17 ‘high-methylation’ tumours display significantly increased TGFB1 expression when compared to CDH17 ‘low-methylation’ CC tumours." (PMID 36612154, 2022). "Knockdown of CDH17 suppresses tumor development and metastasis in GC, HCC, CRC and PC." (PMID 36435809, 2022).